SNAPC2 (small nuclear RNA activating complex polypeptide 2)
Description:
Part of the SNAPc complex required for the transcription of both RNA polymerase II and III small-nuclear RNA genes. Binds to the proximal sequence element (PSE), a non-TATA-box basal promoter element common to these 2 types of genes. Recruits TBP and BRF2 to the U6 snRNA TATA box.
Synonyms: SNAP45; PTFdelta
Tractability: PROTAC: ubiquitination databases record sites on it.
Gene: Protein-coding gene on chromosome 19 (7,920,320 to 7,923,250, forward strand). Ensembl gene ENSG00000104976.
Subcellular location: Nucleus
Subcellular location (Human Protein Atlas): Nuclear bodies; Nucleoplasm; Cytosol
Pathways (Reactome):
Gene expression (Transcription): RNA Polymerase III Abortive And Retractive Initiation; RNA Polymerase III Transcription Initiation From Type 3 Promoter; RNA polymerase II transcribes snRNA genes
Gene Ontology:
Molecular function: RNA polymerase II general transcription initiation factor activity
Biological process: snRNA transcription; snRNA transcription by RNA polymerase II; snRNA transcription by RNA polymerase III; transcription by RNA polymerase II; transcription by RNA polymerase III
Cellular component: nuclear body; nucleoplasm; snRNA-activating protein complex; nucleus
Genetic constraint (gnomAD): Loss-of-function variants: 29 observed, 21.93 expected, observed/expected ratio (o/e) 1.32, 90% interval 0.98 to 1.77. The synonymous counts are far from expectation, so gnomAD's model fits this gene poorly and the ratio says little. Missense variants: 552 observed, 431.64 expected, observed/expected ratio (o/e) 1.28, 90% interval 1.19 to 1.37. Synonymous variants: 268 observed, 192.65 expected, observed/expected ratio (o/e) 1.39, 90% interval 1.26 to 1.54.
Homologues: Orthologues: chimpanzee SNAPC2 (99% identical), macaque SNAPC2 (95% identical), pig SNAPC2 (75% identical), dog SNAPC2 (72% identical), guinea pig SNAPC2 (70% identical), rabbit SNAPC2 (67% identical), rat Snapc2 (66% identical), mouse Snapc2 (64% identical), zebrafish snapc2 (29% identical), tropical clawed frog snapc2 (28% identical).
Diseases named in the same sentence as SNAPC2 in open-access papers:
SNAPC2 is named in the same sentence as 9 diseases in open-access papers, as found by Europe PMC text mining. Sharing a sentence is not in itself a finding about the gene and the disease. The quoted sentences say what the papers report.
glioblastoma (1 paper, 2019). The most malignant astrocytic tumor (WHO grade IV). "A recent genome-wide methylation study proposes SNAPC2 as a biomarker for glioblastoma prediction." (PMID 31552087, 2019).
liver cancer (1 paper, 2025). An epithelial or non-epithelial malignant neoplasm that arises from the liver. "The present study provides targets of genes or pathways for therapeutic as well as diagnostic strategies in the future and firstly reveals the effect as well as underlying mechanisms of SNAPC2 on improving liver cancer prognosis." (PMID 40465781, 2025). "In summary, as a critical transcription factor, SNAPC2 not only provides novel insights into the mechanisms underlying liver cancer but also represents a promising therapeutic target for the treatment of this disease." (PMID 40465781, 2025). "SNAPC2 activation is associated with several cancer-promoting pathways in liver cancer samples." (PMID 40465781, 2025). "Moreover, this study firstly identified and verified the effect as well as underlying mechanisms of SNAPC2 on improving liver cancer prognosis, enhancing the understanding of SNAPC2 for liver cancer prognosis." (PMID 40465781, 2025). "To further investigate the role of SNAPC2 in liver cancer, we performed single-gene GSEA (Gene Set Enrichment Analysis) on two datasets." (PMID 40465781, 2025). "Based on the survival analysis on SNAPC2, we confirmed that the lower expression of SNAPC2 was related to the better prognosis of liver cancer." (PMID 40465781, 2025). "The results of CCK-8 assay and colony-forming assay indicated that the liver cancer cells with lower/higher expression of SNAPC2 possessed lower/higher level of proliferation." (PMID 40465781, 2025). "The result of flow cytometry showed that the apoptosis of liver cancer cells with lower SNAPC2 expression was more than that of cells with higher SNAPC2 expression." (PMID 40465781, 2025). "Moreover, the effect of SNAPC2 on improving prognosis were verified and demonstrated was through decreasing proliferation as well as migration of liver cancer cell and increasing apoptosis of liver cancer cell." (PMID 40465781, 2025). "In this present study, we firstly explored the effects of SNAPC2 on liver cancer." (PMID 40465781, 2025). "Furthermore, as a transcription factor, SNAPC2 plays a crucial role in the mechanistic understanding of liver cancer." (PMID 40465781, 2025). "Moreover, reduced SNAPC2 expression in HepG2 cells led to decreased proliferation and migration, and increased apoptosis, suggesting SNAPC2 plays a role in liver cancer progression by promoting cell proliferation and migration." (PMID 40465781, 2025). "Moreover, lowering SNAPC2 expression could improve the prognosis of liver cancer through decreasing proliferation and migration s and increasing apoptosis of cancer cell." (PMID 40465781, 2025). "Through regulating these pathways, SNAPC2 may drive the progression of liver cancer." (PMID 40465781, 2025). "We hypothesize that SNAPC2, as a crucial transcription factor, may promote the transcription of key factors in these pathways, thereby activating downstream signaling and contributing to the progression of liver cancer." (PMID 40465781, 2025). "Especially, there were no researches about SNAPC2 affecting liver cancer." (PMID 40465781, 2025).
liver disease (1 paper, 2026). "While Snapc2 and Ccl25 have been associated with liver disease, the function of Ppr36 has not been fully eluded even though it’s locus hosts variants associated with lipid metabolism by GWAS." (PMID 41544130, 2026).
cancer (2 papers, 2024 to 2025). A tumor composed of atypical neoplastic, often pleomorphic cells that invade other tissues. "Additionally, Gene Set Enrichment Analysis (GSEA) of SNAPC2 revealed its involvement in cancer-related pathways." (PMID 40465781, 2025).
tumor (1 paper, 2025). "Our analysis indicates that SNAPC2 activates several key oncogenic pathways, including MYC, E2F, Notch, and PI3K signaling pathways, all of which are closely associated with tumor proliferation, metabolic reprogramming, and malignant transformation." (PMID 40465781, 2025). "The result of model with 10 genes showed that 6 genes of MYCN, NDRG1, TXNRD1, SNAPC2, PHOSPHO2 and CDCA8 were more significantly associated with diagnosis of tumor according to the statistical filter of P < 0.05." (PMID 40465781, 2025). "Furthermore, SNAPC2 enhances glycolysis and epithelial-mesenchymal transition (EMT) in cancerous samples, which may promote tumor cell invasiveness and metastatic potential." (PMID 40465781, 2025).
SNAPC2 also shares sentences with these, for which no sentence is quoted: COVID-19 (1 paper); endometriosis (1); glioma (1); oligodendroglioma (1).